CYP1A1 (cytochrome P450 family 1 subfamily A member 1)
Diseases named in the same sentence as CYP1A1 in open-access papers (continued):
Sharing a sentence is not in itself a finding about the gene and the disease.
cancer (continued). "Although a large body of experimental results points towards a positive association of CYP1A1 genetic polymorphisms and cancer occurrence, further investigation is required for such findings to be extrapolated successfully to human populations." (PMID 19531241, 2009). "To ascertain the potential association between functional phenotypes in cancer development and CYP1A1 A-to-I RNA editing, we introduced Flag-tagged wild-type CYP1A1 and edited CYP1A1 (CYP1A1_I462V) expression constructs into A549 and H1299 cell lines, respectively." (PMID 40175891, 2025). "Two functionally important single-nucleotide polymorphisms (SNPs) have been identified in the CYP1A1 gene with regard to cancer susceptibility: a T to C base substitution in the 3′-UTR and an A to G transition resulting in a valine-to-isoleucine substitution at codon 462 (I462V)." (PMID 40175891, 2025). "We have shown that having any polymorphic allele for the CDC25C rs3734166 (genotypes GA and AA) and CYP1A1 Msp1 rs4646903 GG risk genotype may accelerate the onset of cancer in LSVH." (PMID 39457514, 2024). "The significant association of the CYP1A1 Msp1 rs4646903 GG genotype with a younger age at any cancer diagnosis highlights the potential role of metabolic enzymes in modulating carcinogen activation and detoxification pathways, thereby accelerating tumorigenesis." (PMID 39457514, 2024). "Additionally, polymorphisms of other genes, e.g., in CTLA4 or CYP1A1, cause an increased incidence of these cancers." (PMID 37242569, 2023). "Another meta-analysis caried out in 2016 included 748 patients with laryngeal cancer and a control group of 1558 individuals; it concluded that the G allele and G/G rs1048943 homozygotes in the CYP1A1 gene were associated with the risk of developing this malignant neoplasm in the Asian population." (PMID 36553620, 2022). "The GG variant of CYP1A1 gene rs1048943 SNP increased the cancer risk by more than two folds." (PMID 33906313, 2021). "The results noted on the last sampling date are difficult to interpret because expression levels were higher in group E. It has been hypothesized that CYP1A1 alleles may increase the risk of cancer because they encode enzymes with higher metabolic activity." (PMID 34350223, 2021). "CYP1A1 showed the highest mean mutation frequency across all cancer types (1.30%)." (PMID 33842355, 2021). "In addition, rs1048943 is one of the common genetic mutant sites in CYP1A1, which is strongly associated with susceptibility to various cancers." (PMID 32457635, 2020). "In addition, several studies have reported that CYP1A1 polymorphisms were significant factors for the susceptibility and pathogenesis of cancer." (PMID 31551930, 2019). "The contribution of CYP1A1 to cancer progression may be associated with the balance of pre-amino acid activation/detoxification and extrahepatic metabolism of dietary natural products." (PMID 31551930, 2019). "Besides AHRR, MYO1G, and CYP1A1, highlighted for having large effect sizes, several other genes implicated by CpGs overlapping between lung and blood are also cancer related." (PMID 30872662, 2019). "Therefore, CYP1A1 genetic variants can alter flavonoid metabolism and subsequently modify the association between flavonoids and the risk of cancer." (PMID 28273931, 2017). "In addition, CYP1A1 GA + GG genotypes were associated with increased cancer risk in low (OR, 2.05; 95% CI, 1.19–3.63), moderate (OR, 1.72; 95% CI, 1.07–2.76), and high (OR, 2.86; 95% CI, 1.83–4.47) HAA intake groups." (PMID 29165164, 2017). "From a biochemical point of view, the high estrogen-2-hydroxylase activity of the CYP1A1 Ile562Val variant may either increase or reduce the susceptibility to cancer depending on its combination with other genetic and environmental risk factors." (PMID 27754415, 2016). "The CYP1A1 TT genotype was associated with a lower risk for c-cancer (OR = 0.39, p = 0.002)." (PMID 26798414, 2016).
cancer (continued). "The allele C of CYP1A1 was a risk for c-cancer (OR = 2.29, p = 0.002)." (PMID 26798414, 2016). "A number of cancers have been shown to be associated with CYP1A1 genotypes." (PMID 24847427, 2014). "Hence, we performed a meta-analysis of all eligible studies to derive a more precise estimation of the relationship between the MspI and Ile462Val polymorphisms of CYP1A1 and an overall cancer risk." (PMID 24391993, 2013). "The interaction between phase II deficient enzymes and a phase I hyperactive enzyme (CYP1A1) is of interest as it can lead to a larger amount of toxic compounds that may play a crucial role in the initiation or progression of UADT cancers." (PMID 24151610, 2013). "The relationship between CYP1A1 variants and cancer risk has been investigated in several studies." (PMID 24151610, 2013). "To date, a number of meta-analyses have been performed to explore the association between the MspI and Ile462Val polymorphisms of CYP1A1 and various cancers including prostate, ovarian, breast, lung, and colorectal cancer and leukemia, to name a few that occur in different ethnic populations." (PMID 24391993, 2013). "Previous studies about CYP1A1 polymorphisms and cancer risk have been inconclusive." (PMID 24391993, 2013). "In Caucasians, the CYP1A1 Val/Val genotype was suggested to be associated with a higher risk of breast cancer, whereas in Chinese and Japanese this amino acid substitution was associated with other types of cancer, such as lung cancer." (PMID 23785672, 2013). "The CYP1A1*4 allele may increase the relative risk of developing this cancer." (PMID 39062040, 2024). "Additionally, the association with cancer risk may be age-dependent due to distinct developmental patterns exhibited by many xenobiotic-metabolizing enzymes, such as cytochrome P450 1A1 (CYP1A1)." (PMID 38485870, 2024). "Cytochrome P450 CYP1A1 helps detoxify the potential carcinogens in tobacco smoke, it was reported that polymorphisms in the coding gene result in variation in the expression and activity levels which alter metabolism and clearance of carcinogens and therefore modify cancer risk." (PMID 28074113, 2017). "Thus, CYP1A1 may affect the metabolism of environmental carcinogens and alter the susceptibility to cancers, including EC." (PMID 25886559, 2015). "Bioinformatic analysis also confirms that one of the top acetaminophen targets interacting with cancer-related genes is the sequences that encode members of the cytochrome P450 superfamily of enzymes (CYP3A4, CYP1A1, CYP1A2)." (PMID 41516250, 2025). "Significant association betweenlung cancer and GSTT1 null genotype (OR = 1.2; 95% CI: 1.0–1.6), and homozygousCYP1A1 Msp1variant allele (CYP1A1*2A and *2B) genotype (OR = 4.7 95% CI: 1.2–19.0)." (PMID 40958859, 2025). "Several reports have demonstrated that resveratrol inhibits the expression of many cytochrome P450 genes, including those encoding CYP1A1, CYP1B1, CYP1A2, and CYP19 in cancer cell lines of different tissue origin in humans." (PMID 40807256, 2025). "Comparing the morphology of treated cells to untreated cells (control group) reveals that increasing the concentration of treatments and incubation time leads to cancer cell death and increased expression of the CYP1A1 gene." (PMID 41386875, 2025). "In healthy PBMCs, co-culture with BxPC-3 cells increased the AHR and CYP1A1 levels, indicating that signals from cancer cells can activate this pathway." (PMID 41357201, 2025). "A significant difference was also observed between Kaplan–Meier curves comparing the age at cancer diagnosis by CYP1A1 rs4646903 SNP genotypes (comparing AA, AG, and GG; log-rank test p = 0.007)." (PMID 39457514, 2024). "Previous research has investigated the link between specific variations in the CYP1A1 gene and higher rates of cancer development of cancer, especially BC, in Caucasian populations." (PMID 39062040, 2024).
cancer (continued). "Induction of CYP1A1 and CYP1B1 is specifically associated with metabolizing BAP to ultimately produce a diol-epoxide which can lead to the development of cancer." (PMID 38706568, 2024). "In CRC cells, coculture of T18 cells with Fn was found to upregulate AhR, cancer stemness markers, CYP1A1, Wnt signaling, and MAPK signaling." (PMID 38448800, 2024). "We detected an increased level of CYP1A1, which has been shown to activate/inactivate anti-cancer agents." (PMID 39175042, 2024). "It has been demonstrated that sulforaphane inhibits the activity of CYP1A1 and CYP1A2 induced by compounds causing cancer, upregulates phase II enzymes like GSTs, and plays an inducing role in enzyme activities when added to the diet." (PMID 39148948, 2024). "As illustrated, the expression of CYP1A1 was primarily identified in cancer cells, while limited expression was detected in other cell types." (PMID 39183447, 2024). "In accordance with the qPCR findings, the WB analyses demonstrated a notable elevation in the protein levels of CCL5, CCR5, and CYP1A1 within the cancer tissues after combination therapy." (PMID 39183447, 2024). "mQTLs of CpG sites cg06639488 (EFNA1), cg12101586 (CYP1A1) and cg14142171 (HLA‐L) was validated by eQTLs at specific cancer tissues, and cg07932199 (ATXN2) provided colocalization evidence of both methylation and susceptibility to multiple cancers." (PMID 37449541, 2023). "CYP1A1 has also been found to be a targetable enzyme in cancer cell line models and xenograft studies of colon and bladder cancers." (PMID 38001897, 2023). "Previous studies indicated that various CYP450 isoforms exhibited an abnormal expression in the tumor microenvironment, for example, low expression of CYP1A1/2 in cancer cells." (PMID 38293248, 2023). "The mRNA expression patterns of CYP1A1 in cancer tissues showed high variability, probably due to poor tissue integrity, freezing, or preservation agents, among others." (PMID 35678668, 2022). "A mouse subcutaneous xenotransplanted tumor model was established, and the expressions of circFLNA, miR-486-3p, XRCC1, CYP1A1, and related genes in the cancer cells and tissues were detected by RT-qPCR, Western blot, or immunohistochemistry." (PMID 33500536, 2022). "Overexpression of AhR in many cancers triggers production of toxic metabolites via overexpression of CYP1A1 and CYP1B1." (PMID 36160406, 2022). "Previous studies have shown that CYP1A1 is a promising target molecule in the prevention and treatment of human malignant tumors." (PMID 36407768, 2022). "Since Phase I and II enzymes show an opposite reaction regarding activation and detoxification of the carcinogens, it was expected that CYP1A1 expression would be higher in cancer samples." (PMID 35409669, 2022). "CYP1A1 and CYP2E1 are the important members of XME family and have been extensively studied as biomarkers for cancer risk prediction." (PMID 35996502, 2022). "Therefore, CYP1A1 expression might be associated with cancer pathophysiology in CC tissues." (PMID 35678668, 2022). "The Mann–Whitney test showed significant differences in the AUDIT score (p = 0.002) and CYP1A1 expression (p = 0.015) between the cancer and control group." (PMID 35409669, 2022). "We found that AHR and CYP1A1 were mainly expressed in cancer cells and immune cells, such as macrophages, and expressed in the nucleus and the cytoplasm." (PMID 34784845, 2021). "The suppressive effects of BCL-2 and CYP-1A1 are interlinked in cancer prognosis through migratory action and tumorigenesis." (PMID 35009072, 2021). "The aim of this work is to determine the frequency of Single Nucleotide Polymorphisms (SNPs) in CYP1A1 (rs1048943, Ile462VaI and rs4646903/MSP1) and CYP1B1 (rs1056836, Leu432Val) genes in patients with CRC cancer." (PMID 33906313, 2021). "RORA was significantly underexpressed in eight cancer types but was overexpressed in KIRC, whereas CYP1A1 was underexpressed in seven cancer types but was overexpressed in COAD." (PMID 33842355, 2021).
cancer (continued). "Among them, circFLNA is a newly discovered gene, and some studies revealed that overexpression of circFLNA, XRCC1, and CYP1A1 can promote survival and malignant development of cancer cells." (PMID 34852712, 2021). "The positive expression of AHR and CYP1A1 differed significantly (P < 0.01) between the normal and cancer groups." (PMID 34784845, 2021). "Only CYP1A1 was significantly underexpressed during cancer progression in five cancer types, which was consistent with alterations in the development of three cancer types, namely, BRCA, KIRC, and LUAD." (PMID 33842355, 2021). "Actually, an estimated two thirds of cancer patients are linked to environmental factors, such as carcinogenic compounds, and different procarcinogens can be activated or detoxicated through phase I enzymes (mainly cytochromes P450 CYP1A1), which could be mediated by activated AhR." (PMID 33278884, 2020). "CYP1A1 plays an important role in the detoxification of environmental carcinogens and the metabolic activation of dietary compounds with cancer preventive activity." (PMID 33542691, 2020). "Normally, BaP entering into the body is first metabolized by cytochrome P450 (CYP1A1, Cytochrome P450 Family 1 Subfamily A Member 1) to release the ultimate carcinogen 7,8-dihydroxy-9,10-epoxy-BaP (BPDE), causing cancers." (PMID 32053893, 2020). "Of the different reactions catalyzed by CYP1A1, the hydroxylation of the aromatic ring vacancy position is considered to be a sign of cancer." (PMID 33542691, 2020). "CYP1A1-dependent metabolic activation of procarcinogens into carcinogens via epoxides is well established in cancer initiation." (PMID 28698457, 2017). "Decades of PAH-treated lab animal studies have shown strong correlations of inducible CYP1A1 with various types of cancer—in tissues in contact with the administered PAH." (PMID 27894333, 2016). "It is worthy to note that despite the presence of methylation at the XRE-1383 site, all untreated cancer cells displayed increased though variable constitutive levels of CYP1A1 (compared to BPH-1)." (PMID 27203547, 2016). "Cytochrome P450 1A1 (CYP1A1) is a phase I enzyme that regulates the metabolism of environmental carcinogens and alter the susceptibility to various cancers." (PMID 27061602, 2016). "Increased expression of CYP1A1 was observed in all cancer lines (PC-3, LNCaP, and DU145) compared to BPH-1 (P < 0.05); and was enhanced further by 5-aza-2′-deoxycytidine treatment (P < 0.01)." (PMID 27203547, 2016). "Do the specific CYP1A1 expression and induction play a role in the development of a particular cancer ligand related?" (PMID 28105425, 2016). "For the interaction of the CYP1A1&COMT, we observed that TC&HL genotypes had a greater risk for c-cancer (OR = 6.07, p = 0.006) and TT&HL genotypes had a protection effect (OR = 0.24, p < 0.001)." (PMID 26798414, 2016). "Among the xenobiotic metabolizing enzymes, CYP1A1, GSTM1 and GSTT1 have been projected as the potential modulators of cancer susceptibility." (PMID 27090234, 2016). "Understanding the nuclear receptor (NR) mediated regulationof CYP expression in these tissues is necessary for identifying cancer riskfactors and developing CYP1A1/1B1-targeted anti-cancer therapeutics." (PMID 29276805, 2016). "CYP1A1 mRNA expression was markedly increased in all cancer cells after treatment indicating that promoter CpG methylation affects CYP1A1 expression." (PMID 27203547, 2016). "In this study we used two human carcinoma cell lines derived from different human epithelial cell types, HepG2 and HeLa, to assess cell type-specific differences in CYP1A1 expression." (PMID 25116688, 2014). "Since epigenetic mechanisms are known to be involved in cell type-specific gene expression, we sought to assess the epigenetic determinants of CYP1A1 induction in these carcinoma cell lines." (PMID 25116688, 2014).
cancer (continued). "Perhaps different cancers with different carcinogenic mechanisms and environmental exposures had disparate responses to CYP1A1 genotypes." (PMID 24391993, 2013). "In an effort to ascertain the role of fucoxanthin in cancer prevention, the present study evaluated the effect of fucoxanthin on the enzyme activities of CYP1A1, 1A2 and 3A4, which are known to be involved in the activation of pro-carcinogens." (PMID 24137426, 2013). "As Phortress and Triflorcas contain a similar heterocyclic moiety, it is reasonable that this part of the molecule plays a relevant role in up-regulating CYP1A1 expression in cancer cells." (PMID 23071625, 2012). "Therefore, polymorphism of CYP1A1 MspI might play different roles in different cancers." (PMID 22846179, 2012). "CYP1A1 is the most up-regulated gene in cancer cells exposed to the benzothiazole derivative Phortress, its precursor (5F-203) or its desfluoro derivative (DF-203), chemotherapeutic prodrugs currently evaluated in clinical trials." (PMID 23071625, 2012). "The induction of CYP1A1 in cancer cells by dietary compounds and their subsequent metabolism to more active agents is an alternative model that can explain the cancer preventative properties of these compounds in pharmacologically relevant concentrations." (PMID 19531241, 2009). "Dietary constituents suppress cancer progression by inhibiting the CYP1A1-catalyzed metabolic activation and the CYP1A1 enzyme induction of carcinogens." (PMID 19531241, 2009). "Of note is that the CYP1A1-catalyzed metabolism of dietary anticancer flavonoids produces compounds that also possess strong cancer preventative activity." (PMID 19531241, 2009). "Utilization of these systems can unravel the exact mechanisms which regulate the expression of CYP1A1 in extrahepatic tissues, and offer insight into the contribution of the latter in cancer progression or prevention." (PMID 19531241, 2009). "Other studies have attempted to explore a differential overexpression of CYP1A1 between tumor and normal cells, which can potentially add to the various applications of the enzyme in cancer pathology and treatment." (PMID 19531241, 2009). "CYP1B1 and CYP1A1 have also been proposed as targets for cancer chemotherapy for their differential and selective overexpression in tumour cells." (PMID 18454852, 2008). "Liberated parent compounds are sequestered and metabolised by sensitive cells only; similarly, CYP1A1 activity and protein expression are selectively induced in sensitive carcinoma cells." (PMID 11953897, 2002). "Additionally, CYP1A1 is involved in both the detoxification of environmental carcinogens and the metabolic activation of dietary compounds with potential cancer-preventive effects." (PMID 41009721, 2025). "The Cytochrome P450 1A1 (CYP1A1) gene plays a crucial role in the production of enzymes involved in the metabolic activation and detoxification of harmful carcinogens, which are essential for genetic susceptibility to cancer." (PMID 41369042, 2025). "Implications of CYP1A1 and CYP1A2 polymorphisms (mainly single-nucleotide polymorphisms—SNPs) have been extensively studied and provide insights into the cancer pathogenesis, risk stratification, response to therapy, and potential therapeutic targets for individuals with specific CYP1A genotypes." (PMID 41516250, 2025). "Studies have also shown that, the CYP1A1 gene polymorphisms was significantly studied fortheir association with C-TPT response towards platinum and taxane and based chemotherapy in different forms of cancer." (PMID 40092865, 2024). "The CYP1A1 rs4646903 risk (GG) and CDC25C rs3734166 polymorphic (GA+AA) genotypes were significantly associated with an increased risk of a younger age at cancer diagnosis (Adj HR: 2.03 [1.01–4.08], p = 0.034 and Adj HR: 1.53 [1.09–2.14], p = 0.015, respectively)." (PMID 39457514, 2024).